CD4 (CD4 molecule)
Diseases named in the same sentence as CD4 in open-access papers (continued):
Sharing a sentence is not in itself a finding about the gene and the disease.
tumor (continued). "Many lymphocytes, mostly CD4+ and CD8+ cells, infiltrated to the tumours of IL-12-treated mice." (PMID 9716025, 1998). "This investigation used monoclonal antibodies, anti-CD4, -CD8 and -CD11c, to identify subsets of tumour-infiltrating mononuclear cells in fine needle aspirates to study whether the presence of such cells correlates with the therapeutic effect of IFN-alpha." (PMID 8845294, 1996). "The generated CD4+ T cells secreted interferon (IFN)-gamma, tumour necrosis factor (TNF)-alpha, TNF-beta, and interleukin (IL)-6 (but not IL-4), and exhibited a high level of cytolytic activity against several tumour cell lines." (PMID 8554971, 1996). "Since an elevated Treg/CD4+ ratio reflects enhanced immune tolerance and suppression of effector T cell proliferation, these findings may indicate an intrinsic immune dysregulation in RPL patients, as reported in reproductive and tumor immunology contexts." (PMID 41484285, 2026). "Furthermore, flow cytometry analysis revealed a significant decrease in CD4+ T cells and an increase in CD8+ T cells within MDA-MB-231 tumor tissue in the B1451-treated group compared to the control group, consistent with the results of multiplex immunofluorescence in MC38-hPD-L1 model." (PMID 41601637, 2026). "Although OVAII-specific CD4+ T cells were detected in draining LN (DLN) of Bpmel-OVAII tumor bearing mice, only Bpmel-OVA but not Bpmel-OVAI or Bpmel-OVA-II exhibited an adjuvant effect, indicating that both MHC I and II epitopes were required for the cell adjuvant effect." (PMID 41348109, 2026). "Furthermore, spleen regeneration had no significant impact on tumor infiltration by CD4+ T‐lymphocytes." (PMID 41522488, 2026). "Interestingly, CD4+ T cells were the predominant cells in the low PRS group versus the high PRS group in tumor and normal tissue, while plasma cells mainly focused on the high PRS group in tumor and normal tissue." (PMID 41262521, 2026). "Conversely, when KLF4 functions as a tumor‐suppressive factor within the TME, as exemplified in lung adenocarcinoma, it downregulates NF‐κB2 and CXCR2, concomitantly restrains tumor cell invasion, and enhances the infiltration of CD4+ and CD8+ T cells, macrophages, and other immune subsets." (PMID 41532367, 2026). "The crucial final effector cells responsible for effective immune surveillance are tumor-specific cytotoxic lymphocytes, mostly CD8+ CTLs but also other types of cytotoxic lymphocytes (NK cells, innate lymphoid cells (ILCs), γδ T cells, NKT cells, MAIT cells and CD4+ T cells)." (PMID 41315764, 2026). "Flow cytometry analysis of tumor tissues revealed a remarkable enhancement in antitumor immunity under HMCZH treatment compared to PBS control: mature DCs increased from 6.17% to 28.9%, intratumoral CD8+ T cells rose from 2.88% to 8.78%, and CD4+ T cells expanded from 2.56% to 13.9%." (PMID 41424843, 2026). "CD3+CD4+ T cells from 4T1 tumors expressed minimal levels of Tnfrsf11b, further emphasizing the differential immune programming induced by metastatic versus nonmetastatic tumor microenvironments." (PMID 41364090, 2026). "Unexpectedly, both CD8+ T cells and NK cells, but not CD4+ T cells, were required for the efficacy of CD40 agonist, even though CD8+ T cells cannot directly recognize antigen presentation-deficient tumor cells." (PMID 41676732, 2026). "Staining with CLTCH129>Q/I-Ak tetramer revealed a distinct population of NeoAg-specific T cells first seen nine days after tumor inoculation which expanded throughout tumor growth without intervention, ultimately comprising approximately 0.1% of total CD4+ T cells in the tdLN (closed symbols)." (PMID 40196575, 2025). "Thus, we performed a multiplex immunohistological (mIHC) analysis to investigate major lymphocytic and myeloid immune cell populations by staining with antibodies for CD4, CD8, Ly6G, CD11b, and F4/80 together with the tumor-epithelial cell marker panCytokeratin." (PMID 40204953, 2025).
tumor (continued). "Additionally, TIMER analysis indicated that CPM expression is correlated with immune cell infiltration, specifically with B cells, CD4+ T cells, CD8+ T cells, macrophages, neutrophils, and dendritic cells, suggesting a potential role for CPM in the tumor microenvironment and immune response." (PMID 40136513, 2025). "Flow cytometry of ascitic fluid showed lower proportions of T cells (CD3+, CD4+, CD8+) and NK cells (CD56+) compared with historical data from cirrhotic ascites, suggesting an immunosuppressive environment potentially driven by high tumor burden and elevated cytokine levels." (PMID 40282458, 2025). "As Treg are the dominant CTLA4-expressing CD4 T cell that could productively interact with MHCII and CD80/86 expressing macrophages, it is notable that these cells have been shown to expand in proportion in the tumor at later timepoints following RT." (PMID 41417245, 2025). "Interestingly, the total amounts of CD4+ and CD8+ T cells decreased in the spleen while increasing in lymph nodes, suggesting a recruitment to the site of tumor development and T and B cells infiltrated the tumor, especially CD8+ T cells." (PMID 39751916, 2025). "Therefore, CD4 + T cells can act as an essential orchestrator of the antitumor immunity in the TME, even in the absence or in addition to direct CD4 + T cell direct tumor cytotoxicity." (PMID 41410746, 2025). "Importantly, the percentage of CD8+ and CD4+ T cells in the ICAM‐1–Dxd plus B7‐H3‐CD3 group was markedly greater than that in the other groups, demonstrating immune cell infiltration in tumor tissues." (PMID 39996528, 2025). "Additionally, TIMER analysis indicated that ITIH2 expression is correlated with immune cell infiltration, specifically with B cells, CD4+ T cells, CD8+ T cells, macrophages, neutrophils, and dendritic cells, suggesting a potential role for ITIH2 in the tumor microenvironment and immune response." (PMID 40136513, 2025). "Despite no obvious change in the total CD4+ T cells with anti-VISTA or RT treatment alone, the FoxP3/CD4+ T cell ratio significantly decreased in the group treated with anti-VISTA alone, suggesting an impact on Treg differentiation or recruitment within the tumor." (PMID 40580480, 2025). "Flow cytometry analysis revealed that CD4+CD8+ T cells increased from 1.39% (control group) to 5.22% (NZCB + US group), while for CD4−CD8+ T cells, the population markedly increased from 16.60% (control group) to 27.50% (NZCB + US group), indicating the activated anti-tumor T cell immunity." (PMID 40739587, 2025). "Though it is not immediately clear why upregulation of CD3 and CD4 would be advantageous for tumor cells, these may reflect an acquired phenotype afforded by the plasticity of a CSC state." (PMID 40707771, 2025). "Only four cell types exhibited significant differences when comparing the three metastatic sites, CAFs, B cells, endothelial cells, and CD4+ T cells, giving the impression of a quantitatively similar metastatic tumor microenvironment, independent of the metastatic site." (PMID 39739693, 2025). "The results demonstrated that CTT triggered significant upregulation of NICD in CD4+ T cells compared to that in tumor-bearing controls, which was abrogated by CD8+ T cell depletion after CTT, indicating that CD8+ T cells are indispensable for CTT-induced Notch1 activation in CD4+ T cells." (PMID 40277945, 2025). "In contrast, tumor-related indicators were positively correlated with the proportion of CD8 + T cells and activated NK cells (P < 0.05) and were significantly negatively correlated with the proportions of resting memory CD4 + T cells and naive B cells (P < 0.05)." (PMID 40833956, 2025). "Our findings indicated an up-regulation of Mpzl1 expression in CD4+ T cells and CD8+ T cells within the spleens of Ddx21MT-immunized mice, suggesting a potential role for high Mpzl1 expression in T cell migration to tumor sites, thereby contributing to anti-tumor immunity." (PMID 39981234, 2025).
tumor (continued). "To elucidate the functions of CD4+ T cells, CD8+ T cells and NK cells within the context of the anti‐tumor response elicited by FAST, we utilized specific depletion antibodies to monitor the anti‐tumor efficacy of FAST following the depletion of the respective immune cells." (PMID 40135850, 2025). "Moreover, the spatially resolved 64Cu-CD4-Nb1-PET data of the TME enables us to forecast treatment resistance, which was further validated through immunofluorescence analysis in both mouse and human NSCLC tumor tissues." (PMID 40561008, 2025). "Furthermore, apCAFs could modulate ratio of CD4+ T cells/CD8+ T cells, such as higher ratio of CD4+ T cells/CD8+ T cells could promote tumor progression." (PMID 39891284, 2025). "Thus, 30.43% of CD4-positive patients (n = 7) and 60.87% of CD4-negative patients (n = 28) had tumor margin infiltration." (PMID 40362599, 2025). "In addition, Tregs have been shown to suppress anticancer immune responses against autologous and tumor-expressing antigens by inhibiting the activation and differentiation of CD4+ helper and CD8+ cytotoxic T cells, thus contributing to tumor occurrence and progression." (PMID 40589741, 2025). "However, we would like to acknowledge that, due to limitations on the number of antibodies can be used at a time for multiplex IHC analysis, we have focused only on immune cell markers (CD4, CD8, CD45), tumor marker (pan CK), MAPK marker (pp38) and nuclei stain (DAPI)." (PMID 40475776, 2025). "Among these cytokines, TNF could induce the CD4+CD25+FoxP3+Treg differentiation, CSF1 and CCL22 drive the differentiation of F4/80+CD11b+ monocytes to macrophages, and IL-23 inhibited CD8+T cell infiltration and promoted inflammation and tumor incidence." (PMID 41184283, 2025). "Notably, anti-CD80/CD86 as a single agent or in combination with radiation also resulted in an overall decrease in CD4 T cells as a percent of live cells in the tumor, without impacting CD8 T cell proportions." (PMID 41417245, 2025). "Overall, our ability to initiate autologous tumor killing by blocking KLRG1’s interactions with E-cadherin nominate KLRG1 not just as a marker of cytotoxic CD4+ T cells with shared tumor specificity, but as an additional regulatory step (separate from PD-1) that can further mobilize killing." (PMID 40299576, 2025). "Therefore, we evaluated the percentages of CD4+ and CD8+ T cells, which are among the main effector cells involved in the eradication of tumor, as well as MDSCs, which can interact with other immune cells to inhibit the immune response and ensure tumor cell survival." (PMID 40033767, 2025). "We also confirmed that the observed death from CD4+ T cell coculture was from tumors (using directly labeled tumor target cells) and not T cells, and that E-cadherin blockade can also enhance CD8+ T cell tumor killing in a KLRG1-dependent manner despite some spontaneous killing activity." (PMID 40299576, 2025). "Notably, although cDC2s and monocyte-derived DCs comprise most of the myeloid APCs in the TME, a recent study showed that tumor-specific T cells were primarily activated in the TME by cDC1s, which functioned simultaneously to support both CD8+ and CD4+ T cell priming." (PMID 41030446, 2025). "Tumor promoter exposure in these mice leads to elevated levels of C-X-C motif chemokine ligand 5 (CXCL5) and macrophage colony-stimulating factor (M-CSF), promoting the accumulation of CD200R+ MDSCs and forkhead box P3 (FoxP3+) regulatory T cells while reducing activated CD4+ T cells in the skin." (PMID 40868818, 2025). "TIMER2.0 analysis showed that overexpression of PRDX1 was negatively correlated with infiltration of CD4+ and CD8+ T cells, while positively correlated with infiltration of M2 macrophages in CRC, suggesting a potential role for PRDX1 in shaping anti‐tumor immunity via macrophage polarization." (PMID 41306557, 2025).
tumor (continued). "Moreover, we found that tumor-infiltrating CAR+CD4+ T28zT2 cells but not CAR+CD4+ 1928zT2 cells upregulated NKG2D expression." (PMID 40107245, 2025). "Notably, no appreciable MHCII/CD4 interactions were predicted for saline control tumor cells and CD4+ T cells, despite that these tumor cells expressed MHCII (albeit at low levels)." (PMID 39885128, 2025). "Interestingly, SDFZ‐8 did not affect PD‐1 expression in tumor‐infiltrating CD4+ T cells and CD8+ T cells, and downregulated PD‐1 expression in tumor‐infiltrating NK cells." (PMID 41267925, 2025). "Indeed, polyclonal HPV-antigen specific CD4+ and CD8+ are identified in both the primary tumor and draining lymph nodes in approximately half of patients and are poised for cytotoxic action upon proper modulation of TIME to help them overcome the exhausted phenotype." (PMID 41007768, 2025). "Furthermore, combining the two therapies resulted in a significant increase in the infiltration of CD4+ and CD8+ cells within tumor tissues and a notable decrease in Treg cells, resulting in a significant reduction in tumor size or even complete eradication in mice." (PMID 39874200, 2025). "As the proportion of lung Foxp3+CD4+ T cells in CD45+ cells positively correlated with day 21 tumor weight (data not shown), depletion of Foxp3+CD4+ T cells by anti-CD4 antibody likely has a stronger effect in augmenting the immune response for the >600 mg tumor than the 95–600 mg tumor group." (PMID 39835538, 2025). "Furthermore, indole-3-aldehyde mediates anti-tumor immunity by activating AhR in CD8+ T cells to promote IFN-γ production, and by promoting the ligand-dependent differentiation of CD4+ T cells into Th17 or Treg cells, ultimately enhancing the efficacy of immune checkpoint inhibitors." (PMID 41050671, 2025). "In silico analysis revealed that the upregulation of BCL10 in tumor immune microenvironment (TIME) was correlation with decreased infiltration of CD8+T cells, CD4+Th1 cells and NK T cells, and increased infiltration of Treg cells and CD4+Th2 cells in most tumors including CESC." (PMID 40539049, 2025). "Besides, the results of tumor microenvironment analysis suggested that ANXA5, STAT1, CD44, CAV1, and ANXA2 expression was positively correlated with the infiltration of B cell, CD8+ T cell, CD4+ T cell, macrophages, neutrophils, and dendritic cells." (PMID 40607003, 2025). "However, the literature on the impact of CD4+CD8+ T cells involved in cancer remains contradictory, with some studies pointing to a cytotoxic function of these cells that contributes to the elimination of tumor cells." (PMID 39858472, 2025). "Meanwhile, the tumor panel could not differentiate between CD8+ or CD4 + T-cells and lacked markers entirely for B-cells and all myeloid lineage cells including macrophages and monocytes." (PMID 40763304, 2025). "Given that LAG3 is expressed in active CD4 + and CD8 + T cells, we can view its elevation as an outward manifestation of the presence of more effector lymphocytes in the tumor tissues, whereas more lymphocytes equate to more active tumor immunity and more benefits for ESCC patients." (PMID 40411616, 2025). "For example, transcriptome profiles of tumor-infiltrating leukocytes isolated from immunotherapy naïve HPV− vs. HPV+ HNSCC tumors revealed that certain cell types, such as B cells, myeloid cells, and conventional CD4+ T cells, have divergent signatures by HPV status." (PMID 40284904, 2025). "CD4+ and CD8+ staining were performed to evaluate the degree of T-cell infiltration and cytotoxic activity within the tumor microenvironment, whereas IFN-γ staining was conducted to assess the functional activation of tumor-infiltrating lymphocytes and the induction of a Th1-type immune response." (PMID 41614850, 2025). "Thus, 25% of CD34-positive patients (n = 6) and 64.44% of CD4-negative patients (n = 29) had tumor margin infiltration." (PMID 40362599, 2025).
tumor (continued). "However, although we found enrichment of KLRG1 on circulating tumor-TCR-matching cytotoxic CD4+ T cells, the functional relevance of this ligand-receptor interaction for tumor recognition and killing in this subset has not been studied." (PMID 40299576, 2025). "Furthermore, depletion studies conducted in vivo showed that CD8+ T cells were critical for STEPT treatment‐mediated tumor suppression, unlike CD4+ T cells." (PMID 41476656, 2025). "Furthermore, CD4+ T cells could inhibit tumor cell cycle progression and activate pro-inflammatory signaling pathways involving TNF and INF-γ, effectively inducing tumor cell regression." (PMID 39859524, 2025). "Tumor bulk RNA-Seq data highlighted that the tumor expression of 5/32 genes (IRF1, IKZF1, SPI1, SH2B3, LAT) was each strongly correlated (Spearman’s ρ > 0.5) with at least one intra-tumor T/myeloid cell infiltration marker (CD4, CD8A, CD11B, CD45) in every one of the cancer types." (PMID 40428397, 2025). "CD68 expression has significant negative relation with tumor purity and significant positive correlation with tumor-infiltrating levels of B cell, CD4+ T cell, CD8+ T cell, macrophage, myeloid dendritic cell and has no relation with cancer associated fibroblast in ESCA." (PMID 40918116, 2025). "Flow cytometry analysis of splenic lymphocytes revealed an increased number of CD4+ and CD8+ T cells in the treatment group compared to the control, indicating that the recombinant virus could induce tumor cell death through the activation of cellular immunity." (PMID 40612869, 2025). "In contrast, type 2, CD4+ Th2 can inhibit CTL activity, promote the proliferation of B-lymphocytes, and may activate an anti-inflammatory immune response that could potentially favor the progression of tumor." (PMID 40141358, 2025). "However, no significant changes were noted in the percentage of CD4+ cells and Tregs in tumor tissues." (PMID 40969744, 2025). "Intriguingly, several papers identified neoantigen-specific T cells preferentially enriched in the proportion of CD8+ and CD4+ T cells expressing PD-1, even suggesting the monitoring of PD-1+ CD8+ T cells as a non-invasive surrogate of neoantigen-reactive T cells residing within the tumor." (PMID 40236706, 2025). "Antitumor-related immune cells, including M1 macrophages, CD8+T cells, and memory CD4 T cells, demonstrated a negative association with the HYP.SIG score in nearly all cancers, whereas tumor-promoting immune cells, such as M2 macrophages, showed a positive association." (PMID 41419193, 2025). "When FL/GM-DCs loaded with B16-OVA tumor lysates were co-cultured with CD4+T cells that had been isolated from OT-II mice, we detected a significant increase in the activation and proliferation of CD44+CD4+T cells relative to those co-cultured with GM/IL4-DCs (37% vs. 25.5%)." (PMID 40977690, 2025). "For instance, certain immune cells, such as CD4 T cells, CD8 T cells and NK cells have the capacity to directly eliminate tumor cells; conversely, other immune cell types (e.g., Tregs) may facilitate tumor growth." (PMID 41185082, 2025). "In addition, there was no significant impairment of Ki67+ tumor cell proliferation nor changes in the tumor infiltration of CD4+, CD8+, FoxP3+ nor Arg1+ cells." (PMID 41226782, 2025). "Notably, the remodeling of immune cells inside the tumor microenvironment, manifested with an increase of CD8 + T cells, CD4 + T cells, DC cells, NK cells, M1 TAMs, and a decrease of Tregs, MDSCs, and M2 TAMs upon the treatment, led to inhibition of tumor growth." (PMID 40797208, 2025). "The triple combination treatment increased circulating IFN-γ levels and enhanced the recruitment of CD4 + T cells, CD8 + T cells, and M1 macrophages within the tumor microenvironment, potentially contributing to an improved antitumor immune response and tumor growth inhibition." (PMID 40836337, 2025).